NDP (norrin cystine knot growth factor NDP)
Diseases named in the same sentence as NDP in open-access papers (continued):
Sharing a sentence is not in itself a finding about the gene and the disease.
Intellectual disability (4 papers, 2006 to 2024). "In such cases, the putative mechanism is a dysfunction of catecholamine metabolism as the cause of the intellectual disability and the NDP deletion as the cause of the ocular phenotype." (PMID 35651932, 2022). "When the coding region of NDP was examined, variants that resulted in a frame shift and premature termination of translation were commonly associated with hearing loss and intellectual disability." (PMID 35651932, 2022). "In this systematic review we summarise all reported NDP variants and draw conclusions about whether the nature of the NDP variant is predictive of the severity of the resulting ocular pathology and associated hearing loss and intellectual disability." (PMID 35651932, 2022). "The second is that intellectual disability arises when norrin signalling is severely disrupted by a large deletion in NDP, resulting in maldevelopment of the cerebral vasculature." (PMID 35651932, 2022). "In addition, in 30% or more of patients, mental retardation is also present, suggesting an important CNS role for NDP." (PMID 24416243, 2014). "Taken together, these findings suggest that MAO A and B deletions cause intellectual disability independent of the NDP deletion, however if an NDP deletion causes a severe enough loss of function it may alone cause intellectual disability." (PMID 35651932, 2022). "Interestingly all cases of NDP deletion that coincide with a MAO A or B deletion, intellectual disability is seen together with a severe retinal phenotype but without hearing loss." (PMID 35651932, 2022).
retinal detachment (4 papers, 2021 to 2022). An eye emergency condition which may lead to blindness if left untreated. "To this end, we suggest that once the patient is found with LRP5 and NDP mutations, it is necessary to always be alert to the occurrence of severe retinal detachment and lifelong monitoring should be carried out." (PMID 35830446, 2022). "According to our statistical analysis, it was found that the most common clinical manifestation of patients with LRP5 and NDP gene mutations was retinal detachment, which was the main cause of vision loss in FEVR." (PMID 35830446, 2022). "In the candidate gene approach, COL9A2, COL9A3, NHEJ1, RS1 and NDP genes were investigated based on their known associations with RD and retinal detachment in dogs and humans." (PMID 33945575, 2021). "Retinal detachment is the most frequent symptom with patients of LRP5 and NDP mutations, accounting for 51.9% and 64.5%, respectively." (PMID 35830446, 2022). "No variations were noted in genes known to cause Wagner syndrome or other retinal detachments (ATOH7, TSPAN12, LRP5, or NDP) or in genes known to cause ocular disease." (PMID 33776059, 2021).
retinal dystrophies (3 papers, 2021 to 2024). "In the group with only ocular involvement, we observed 6 cases of (probably) pathogenic variants in genes associated with retinal dystrophies (RPGR; N = 2, CACNA1F; N = 2, RP2, NDP), which corresponds to 27.3% of all genetically confirmed cases of HM." (PMID 39495751, 2024). "Among cases of high myopia with ocular involvement (38.9%), a genetic cause was found in 8 out of 14 probands, including (likely) pathogenic variants in genes related to retinal dystrophies (CACNA1F, RPGR, RP2, NDP)." (PMID 39495751, 2024). "Specifically, HM was identified in six children with retinal dystrophies (RPGR; N = 2, CACNA1F; N = 2, RP2, NDP) and one child each of corneal dystrophy (ZEB1) and Stickler syndrome (causative variant in the COL9A2 gene)." (PMID 39495751, 2024).
Alpha-thalassemia (2 papers, 2020 to 2023). Alpha-thalassemia is an inherited hemoglobinopathy characterized by impaired synthesis of alpha-globin chains leading to a variable clinical picture depending on the number of affected alleles. "In this study, we applied HLRS method based on 10× Genomics sequencing to successfully phase haplotypes in samples from patients who were carriers of alpha thalassemia or NDP gene disorder." (PMID 32819358, 2020). "Two families were selected to validate this method; one with alpha thalassemia and the other with NDP gene disorder." (PMID 32819358, 2020). "In this study, we applied HLRS method to successfully phase haplotypes in samples from patients who were carriers of alpha thalassemia or NDP gene disorder, without including their family members." (PMID 32819358, 2020).
amyloid (2 papers, 2018 to 2022). "Since the process of amyloidosis and, as a consequence, microgliosis is slower in 3xTg mice, we hypothesize that NDP treatment is more effective on microgliosis in earlier stages of AD pathology progression." (PMID 36703981, 2022). "In addition, we identified norrin (NDP) and collagen alpha-2(VI) (COL6A2) as highly selective markers that are clearly present in CAA yet virtually absent in relation to parenchymal amyloid plaque pathology." (PMID 29860944, 2018).
colon cancer (2 papers, 2016 to 2017). "We also found tumor cell selective expression of the NDP, FZD4, and TSPAN12 genes, encoding norrin, its receptor frizzled 4, and a norrin signal-amplifying component of the receptor complex, respectively, which were linked to colon cancer angiogenesis in a recent study." (PMID 27215396, 2016).
glioma (2 papers, 2017 to 2025). A benign or malignant brain and spinal cord tumor that arises from glial cells (astrocytes, oligodendrocytes, ependymal cells). "The integrated analysis of the Cancer Cell Line Encyclopedia (CCLE) and The Cancer Genome Atlas (TCGA) datasets revealed ubiquitous NDP expression across multiple malignancies, with the highest expression levels observed in the glioma cell lines and primary glioblastoma specimens." (PMID 41357583, 2025).
Insulin resistance (2 papers, 2011 to 2024). Increased resistance towards insulin, that is, diminished effectiveness of insulin in reducing blood glucose levels. "Interestingly, in the NDP group, at week 16, we observed an early-onset insulin resistance with elevated pancreatic β-cell consistent with high corticosterone concentration compared to the other weeks." (PMID 38791468, 2024). "In future it has to be validated if the other most differentially regulated genes between both tissues such as: SGCD, LCE3D, EREG, NDP and CXCL9, FSTL3, PDZK1IP1 could be used as biomarkers related to insulin resistance of adipose or liver tissues respectively." (PMID 21978410, 2011).
lung carcinoma (2 papers, 2021 to 2023). "Furthermore, ECA has been demonstrated to suppress the epithelial-mesenchymal transition (EMT) process induced by SPC or TGF-β1 in lung cancer cells by inhibiting Wnt activation via downregulation of NDP expression." (PMID 37047688, 2023). "ECA inhibited metastasis of lung cancer cells via the blocking of NDP-induced Wnt signaling." (PMID 37047688, 2023). "NDP is a broad-spectrum anticancer drug, and it may be used in the treatment of malignant tumors, such as cervical, nasopharyngeal, esophageal, and lung cancer." (PMID 34229692, 2021).
retinitis pigmentosa (2 papers, 2021 to 2022). Retinitis pigmentosa (RP) is an inherited retinal dystrophy leading to progressive loss of the photoreceptors and retinal pigment epithelium and resulting in blindness usually after several decades. "These six SP variants were in the CRB1 (early-onset retinal dystrophy), NDP (familial exudative vitreoretinopathy) (FEVR), FZD4 (FEVR), EYS (retinitis pigmentosa), and RS1 (X-linked juvenile retinoschisis) genes." (PMID 36362148, 2022).
Alzheimer disease (1 paper, 2014). A progressive, neurodegenerative disease characterized by loss of function and death of nerve cells in several areas of the brain leading to loss of cognitive function such as memory and language. "Future studies incorporating gain and loss of function of NDP should help clarify NDP's potential role in neurogenesis and Alzheimer disease." (PMID 24416243, 2014).
aortic stenosis (1 paper, 2026). Aortic valve stenosis is a aortic valve disease caused by the incomplete opening of the aortic valve. "We also observed two signals on the X chromosome, in loci near NDP (for the gradient-based measures) and near TSPAN6 (for AVA), both of which have not been described for aortic stenosis or aortic valve disease before." (PMID 41419685, 2026).
breast carcinoma (1 paper, 2023). "Subsequently, we determined the effect of treatment with NDP-MSH and MSG-606 on breast cancer cell growth." (PMID 37679505, 2023).
erythropoietic protoporphyria (1 paper, 2023). A rare congenital metabolic disorder characterized by an inborn error of porphyrin-heme biosynthesis. "NDP-MSH is an approved drug currently used to prevent skin damage from sun exposure in people with erythropoietic protoporphyria." (PMID 38110615, 2023).
gastric cancer (1 paper, 2025). A primary or metastatic malignant neoplasm involving the stomach. "The cellular level expression of NDP is increased in gastric cancer parenchymal cells, but it remains undetected or has the lowest expression in endothelial cells." (PMID 41357583, 2025).
glioblastoma (1 paper, 2025). The most malignant astrocytic tumor (WHO grade IV). "In glioblastoma (GBM), the most common and aggressive malignant primary brain tumor, belongs to the family of astrocytic tumors, elevated NDP expression was significantly associated with prolonged survival, especially in patients with low ASCL1 expression levels." (PMID 41357583, 2025).
hematoma (1 paper, 2019). A hematoma is a collection of blood from a vascular structure into an extravascular space. "We investigated whether the anti-inflammatory function of NDP-MSH was associated with the decrease in the numbers of microglia in peri-hematoma tissue." (PMID 31660977, 2019).
Hypertension (1 paper, 2018). The presence of chronic increased pressure in the systemic arterial system. "NDP immunoreactivity was only mildly increased in CADASIL and hypertension related small vessel disease." (PMID 29860944, 2018).
ischemia (1 paper, 2025). A hypoperfusion of the BLOOD through an organ or tissue caused by a PATHOLOGIC CONSTRICTION or obstruction of its BLOOD VESSELS, or an absence of BLOOD CIRCULATION. "This ischemia-driven process induces compensatory vessel thickening and narrowing, as demonstrated in NDP knockout models." (PMID 40739591, 2025).
liver cancer (1 paper, 2022). An epithelial or non-epithelial malignant neoplasm that arises from the liver.
medulloblastoma (1 paper, 2021). A malignant, invasive embryonal neoplasm arising from the cerebellum. "Blockage of Norrin, the protein product of the NDP gene, in SHH medulloblastoma has been shown to create a tumor-permissive, stromal-driven microenvironment." (PMID 34667228, 2021).
myeloma (1 paper, 2014). "Since as far as we know NDP has not been related to myeloma, our data suggest a putative role for this factor in the pathophysiology of the disease and in the development of ostelytic lesions." (PMID 25268740, 2014).
nasopharyngeal carcinoma (1 paper, 2021). A carcinoma arising from the nasopharyngeal epithelium. "However, NDP treatment led to autophagosome accumulation and increased LC3-II expression in cisplatin-sensitive nasopharyngeal cancer cell lines." (PMID 34229692, 2021).
ovarian carcinoma (1 paper, 2016). A malignant neoplasm originating from the surface ovarian epithelium. "Intriguingly, we identified NDP, FZD4, and TSPAN12 to be associated with a delayed tumor progression, thus pointing to a novel tumor suppressor function of this signaling pathway in ovarian cancer." (PMID 27215396, 2016).
peripheral vascular disease (1 paper, 2023). Any disorder affecting blood flow through the veins or arteries outside of the heart. "AAV9.NDP gene replacement may also have potential for treatment of peripheral vascular disease symptoms in Norrie patients." (PMID 37642150, 2023).
retinoschisis (1 paper, 2021). An inherited or acquired disorder characterized by splitting of the retina into two layers. "There is also a report on familial retinoschisis patients harboring digenic variations in RS1 and NDP genes, yet, segregating only with XLRS pathology." (PMID 34039417, 2021).
subarachnoid hemorrhage (1 paper, 2019). A serious neurological disorder characterized by intracranial hemorrhage into the subarachnoid space. "Following subarachnoid hemorrhage, treatment with NDP-MSH reduced vasospasm and inflammation through the decrease in the phosphorylation of extracellular-signal-regulated kinases (ERK1/2)." (PMID 31660977, 2019).
viral infection (1 paper, 2025). "All the genes involved in the conversion from NDP to dNDP are core genes of the group of flagellated-protist-infecting viruses, implying their essential roles in viral infection." (PMID 40155463, 2025).
X-linked recessive disease (1 paper, 2022). X-linked recessive form of disease. "Because ND is an X-linked recessive disease and the expectant mother was a carrier of the NDP gene variant, prenatal diagnosis of the fetus was considered." (PMID 36035112, 2022).
retinopathies (8 papers, 2020 to 2025). "The pathological phenotype that may result from a disease-causing NDP variant is quite diverse but generally comprises a consistent cluster of features that vary predictably with severity of retinopathy." (PMID 35651932, 2022). "It has been elucidated that NDP p.H43R and NDP H43Q are associated with Norrie (MIM#310600), an inherited retinal disorder of highly overlapping ocular manifestations with FEVR." (PMID 32420371, 2020). "However, the precise relationship between variations in the NDP gene and retinopathy remains to be fully elucidated." (PMID 38146894, 2023). "FEVR is an inherited retinal disorder characterized by incomplete retinal vascular development and secondary retinal changes, and has been reported to be associated with Wnt signaling genes (FZD4, TSPAN12, and NDP) polymorphism." (PMID 35022017, 2022). "Therefore, this study also suggests the dog may serve as a useful model for understanding human NDP-related retinopathies and the development of gene and other therapies." (PMID 33945575, 2021).
cancer (7 papers, 2017 to 2025). A tumor composed of atypical neoplastic, often pleomorphic cells that invade other tissues. "The upregulated genes, including WNT11, HAPLN1, FGF10, BBOX1, CXADR, NDP, and EREG are associated with tumor proliferation, migration, and cancer stemness." (PMID 35954313, 2022). "In recent years, a number of studies have shown the molecular mechanism of NDP in cancers, and the NDP potentially involved multiple potential mechanisms." (PMID 34229692, 2021). "Studying these molecular targets also provides novel theoretical foundation for understanding the molecular mechanisms of cancer, as well as novel drugs to replace NDP for cancer treatment." (PMID 34229692, 2021). "DHM may be combined with or replace other chemotherapeutic drugs, such as NDP, in cancer therapy." (PMID 34229692, 2021).
tumor (7 papers, 2016 to 2025). "Tumor accumulation was significantly inhibited by co-injection of excess amounts of NDP-MSH (p < 0.05)." (PMID 39828865, 2025). "Accordingly, hyperacetylation/upregulation of oncogenes related with angiogenesis and vascular invasion (COL24A1, NDP and HOXA13) and hypoacetylation/downregulation of angiogenesis-tumor suppressor genes (CD40 and IL15) was identified in this study." (PMID 35740301, 2022).
central nervous system disease (1 paper, 2019). "NDP-MSH had been reported to possess multiple beneficial properties in a central nervous system disease, including anti-inflammation, anti-apoptosis, and anti-oxidation." (PMID 31660977, 2019).
NDP also shares sentences with these, for which no sentence is quoted: exudative vitreoretinopathy (16 papers); Blindness (3); persistent fetal vasculature syndrome (3); cataract (2); deafness (2); familial exudative vitreoretinopathy 2 (2); genetic disorder (2); Leber hereditary optic neuropathy (2); leprosy (2); MELAS (2); X-linked retinal dysplasia (2); adenoma (1); albinism (1); aortic valve disease (1); Ataxia (1); Bardet-Biedl syndrome (1); brain edema (1); CADASIL (1); choroideremia (1); ciliopathies (1); Cognitive impairment (1); congenital blindness (1); congenital cataracts (1); corneal dystrophy (1); diabetic retinopathy (1); endolymphatic hydrops (1); epilepsy (1); fragile X syndrome (1); hearing loss (1); Hunter syndrome (1).
A further 25 diseases each share a sentence with NDP in 1 paper.